EIF3F (eukaryotic translation initiation factor 3 subunit F)
Diseases named in the same sentence as EIF3F in open-access papers (continued):
Sharing a sentence is not in itself a finding about the gene and the disease.
Rett syndrome (1 paper, 2021). A severe neurodevelopmental disorder affecting the central nervous system.
spinocerebellar ataxia type 8 (1 paper, 2023). Spinocerebellar ataxia type 8 (SCA8) is a subtype of type I autosomal dominant cerebellar ataxia (ADCA type I) characterized by cerebellar ataxia and cognitive dysfunction in almost three quarters of patients and pyramidal and sensory signs in approximately a third of patients. "EIF3F has been previously implicated in Spinocerebellar ataxia type 8 (SCA8) associated RAN translation of polySer products from CAG repeats." (PMID 37352983, 2023).
cancer (18 papers, 2010 to 2025). A tumor composed of atypical neoplastic, often pleomorphic cells that invade other tissues. "In cancer cells, the loss of eIF3f results in an increased binding of hnRNP K to rRNA, reducing rRNA degradation, and possibly favoring oncogenesis through increased translation." (PMID 28083147, 2016). "The loss of eIF3f seems to contribute to tumorigenesis whereas its ectopic expression is sufficient to restore apoptosis in cancer cells." (PMID 23354061, 2013). "eIF3f expression is downregulated in most cancer cells because of the loss of the eIF3f allele." (PMID 26988917, 2016). "To study the link between human EIF3F overexpression and neoplasia, we generated EIF3F-A549 LUAD cancer cells that overexpressed a flagged-EIF3F ectopic subunit of the human EIF3 complex." (PMID 31527668, 2020). "In the present study, we combined cell biology, genetic, and biochemistry approaches to clarify the biological function of EIF3F in human cancer cells." (PMID 31527668, 2020). "We provide a unique set of data demonstrating that EIF3F regulates the metastatic process by remodeling the proteome, the transcriptome and the bioenergetics of cancer cells." (PMID 31527668, 2020). "We also observed this tumor suppressive effect of EIF3F overexpression in H1975, HeLa, and H460 human cancer cell lines." (PMID 31527668, 2020). "To assess the impact of EIF3F ectopic overexpression on cancer biology, we generated an in vivo orthotopic mouse model of human LUAD using EIF3F-A549 cells expressing luciferase." (PMID 31527668, 2020). "EIF3F was recently discovered in the nucleus of human cancer cells and was proposed to participate in DNA-related functions." (PMID 31527668, 2020). "In particular, we observed that EIF3F overexpression had opposite effects on cancer cell proliferation and migration." (PMID 31527668, 2020). "In the current study, we clarified the molecular regulation and role of different CLU isoforms in cancer development by performing Y2H screening, which revealed that eIF3f is a CLU-interacting protein." (PMID 26988917, 2016). "Previously, qRT-PCR experiments revealed that eIF3f was downregulated significantly in cancer cell lines." (PMID 26988917, 2016). "Previous studies revealed that eIF3f expression was downregulated in most human tumors compared with normal tissues using a cancer profiling array and qRT-PCR." (PMID 26988917, 2016). "Upregulation of eIF3a, eIF3b, eIF3c, eIF3d, eIF3e, eIF3h, and eIF3i along with reduced levels of eIF3e and eIF3f has been observed in several cancers." (PMID 28083147, 2016). "It has been demonstrated that eIF3f expression is significantly decreased in many human cancers, a fact which plays an important role in human cancer." (PMID 24678890, 2014). "The translation system indicated that, in mammalian cells, eIF3f was a negative regulator of translation, which played an important role in human cancer." (PMID 24678890, 2014). "Increased levels of eIF3f expression are found to compromise proliferation and promote apoptosis in cancer cells, of which this pro-apoptotic property of eIF3f is presumably dependent on its interplay with CDK11 and the mammalian target of rapamycin (mTOR)." (PMID 23725059, 2013). "Using a cancer profiling array and real-time reverse transcription PCR, eIF3f transcript levels have been shown to be downregulated in most human tumors relative to matched normal tissues." (PMID 23354061, 2013). "The molecular mechanism by which eIF3f protein expression decreases, contributing to cancer development, is unclear." (PMID 23354061, 2013).
cancer (continued). "It remains to be investigated whether the targets of eIF3f determine the functional outcome of eIF3f expression in various types of cancers and how the context‐dependent expression level of eIF3f occurs." (PMID 37544925, 2023). "Therefore, our findings demonstrate that EIF3F overexpression confers to cancer cells most molecular and bioenergetic attributes of metastatic cells." (PMID 31527668, 2020). "For example, eIF3f is downregulated in various cancers, including gastric cancer." (PMID 31423012, 2019). "Except EIF3E and EIF3F found down-regulated and conferred tumor suppressive activity in cancers, majority of EIF3 members including EIF3A, EIF3B, EIF3C, EIF3D, EIF3H, EIF3I and EIF3M were up-regulated and played important roles in tumor progression of multiple cancer types." (PMID 29568350, 2018). "Therefore, we compared eIF3f mRNA levels in six human cancer cell lines (Miapaca-2, BxPc-3, HeLa, CASKI, SKOV3, and 2774) and a normal cell line (HEK293a) using qRT-PCR." (PMID 26988917, 2016). "The overexpression of eIF3f retarded cancer cell growth significantly and induced apoptosis." (PMID 26988917, 2016). "Therefore, we next evaluated the effect of eIF3f on cancer cell growth by transfecting HeLa and BxPc-3 cells with empty vector or an eIF3f expression vector, and then monitored the growth rates for 24-72 h." (PMID 26988917, 2016). "The identification of this novel function of eIF3f as a sCLU inhibitor might open novel avenues for developing improved strategies for CLU-targeted anti-cancer therapies." (PMID 26988917, 2016). "Previous studies have identified eIF3f as a protein involved in apoptotic signaling as a negative regulator of translation and have also demonstrated that eIF3f expression significantly decreased in many human cancers, and thus played an important role in human cancer." (PMID 24678890, 2014). "We demonstrated that eIF3f expression significantly decreased in many human cancers." (PMID 22457825, 2012). "However, there is a discrepancy regarding eIF3f's role in cancer." (PMID 37544925, 2023). "Therefore, we hypothesized that the participation of EIF3F in the cancer cells malignancy could involve unknown nuclear mechanisms that require partnering with unidentified proteins including genetic regulators of carcinogenesis." (PMID 31527668, 2020). "Therefore, eIF3f inhibits cancer cell growth and induces apoptosis by inhibiting sCLU function." (PMID 26988917, 2016). "Therefore, eIF3f reduced cancer cell proliferation significantly." (PMID 26988917, 2016). "No mutations are responsible for the decreased eIF3f expression in these two cancer types." (PMID 23354061, 2013). "Thus, our data uncovers eIF3f is a critical cancer biomarker regulating SGOC pathway and provides novel insights into targeting eIF3f‐PHGDH axis as potential CRC treatment strategies." (PMID 37544925, 2023). "Studies have confirmed that a decrease in eIF3f expression contributes to cancer development, but the molecular mechanism has not yet been fully elucidated." (PMID 35883466, 2022). "Moreover, diminished eIF3f was detected in CD34+ cells exposed to MSC conditioned medium, which was in line with common suppression in diverse cancers." (PMID 34072546, 2021). "The tumors were first stratified based on the expression of EIF3F in the cancer tissue as compared to that determined in the noncancer tissue." (PMID 31527668, 2020). "However, the regulations and biological activities of eIF3f were not fully characterized in cancers." (PMID 37544925, 2023). "Interestingly, a large number of proteins upregulated in the proteome of EIF3F-overexpressing cells belong to the β-catenin signaling pathway, and recent studies revealed that STAT3 cooperates with β-catenin via direct physical interaction to promote cancer cell malignancy and chemoresistance." (PMID 31527668, 2020).
tumor (17 papers, 2012 to 2026). "We confirmed global epigenetic modification associated with reduced H4R3me2S and re-expression of tumour suppressors, such as EIF3F, FOXP4, ZBTB4, GANAB, TMEM141, in association with loss of clonogenicity." (PMID 33795785, 2021). "Low eIF3f expression in GC was significantly associated with more advanced tumor stages (P = 0.02) and likelihood of recurrence (P = 0.04)." (PMID 24678890, 2014). "We also showed that restored eIF3f expression in tumor cells causes ribosomal RNA (rRNA) degradation, inhibits translation and cell proliferation, and induces apoptosis." (PMID 22457825, 2012). "In tumor cells, loss of eIF3f leads to increased binding of hnRNP K to rRNA, as well as imbalanced rRNA homeostasis and translation." (PMID 22457825, 2012). "Probably, these various multiproteins complexes are implicated in the role of eIF3f in discriminating the mRNAs to be translated into normal cells, and may also reflect the deregulation of the translational pathway in tumor cells." (PMID 23354061, 2013). "Next, we established PDX model for testing the drug efficacy of combined treatment on CRC tumor growth in two CRC PDX sets (eIF3f high versus eIF3f low), and the expressing levels of eIf3f were characterized by immunoblotting." (PMID 37544925, 2023). "The result showed that using doxycycline inducing sh‐eIF3f, knockdown of eIF3f suppressed tumor growth in vivo." (PMID 37544925, 2023). "Here, it is demonstrated that eIF3f is upregulated in CRC tumor tissues and that both Wnt and EGF signaling pathways are participating in eIF3f's oncogenic impact on targeting phosphoglycerate dehydrogenase (PHGDH) during CRC development." (PMID 37544925, 2023). "Accordingly, the M1 population, which regroups individuals developing metastasis, was increased in the subgroup of patients with high EIF3F tumor expression." (PMID 31527668, 2020). "After 4 weeks, the tumor volume was reduced by a factor of three (p < 0.05) when EIF3F was overexpressed in the injected A549 cells." (PMID 31527668, 2020). "Measurement of tumor volume revealed that EIF3F ectopic overexpression significantly reduced the tumor size in vivo." (PMID 31527668, 2020). "Collectively, these results clearly demonstrate that eIF3f can be a potent tumor suppressor in this animal model." (PMID 26988917, 2016). "Herein, we suggest a possible mechanism behind the eIF3f-induced inhibition of tumor growth that involves the direct binding of eIF3f to CLU, which inhibits sCLU-induced activation of Akt and ERK signaling." (PMID 26988917, 2016). "eIF3f levels were correlated with more advanced tumor stages and likelihood of recurrence (all P <0.05)." (PMID 24678890, 2014). "Univariate Cox regression analysis showed that clinical variables, including tumor size (log-rank, P = 0.03), tumor recurrence (log-rank, P <0.01), and eIF3f expression (log-rank, P = 0.04) were all significantly associated with overall survival." (PMID 24678890, 2014). "Immunoscores were calculated when the presence of eIF3f deposits in tumor glands and cytoplasmic staining were positive." (PMID 24678890, 2014). "Transcriptome analysis has shown that endogenous eIF3f expression level changes from one cell type to another and from normal to tumor cells." (PMID 23354061, 2013). "The protein eIF3f is the p47 subunit of the eIF3 complex which plays an important role in translation initiation and whose over-expression, in tumor cells, inhibits cell proliferation and induces apoptosis." (PMID 22916271, 2012). "Together, these observations suggested that eIF3f is a tumor suppressor candidate." (PMID 41423661, 2025). "Overexpression of tumour suppressors, such as EIF3F, FOXP4, ZBTB4, GANAB, TMEM141 was observed." (PMID 33795785, 2021). "This gene module identified in our study provides a molecular signature for EIF3F overexpression that could be used for bioinformatic studies on large datasets of tumor transcriptomes and proteomes." (PMID 31527668, 2020).
tumor (continued). "In contrast, eIF3f treated tumor exhibited large areas of apoptotic cells." (PMID 26988917, 2016). "Additionally, the decreased expression of eIF3f protein was significantly related to more advanced tumor stages (P = 0.02) and likelihood of recurrence (P = 0.04)." (PMID 24678890, 2014). "Furthermore, multivariate Cox regression analyses showed that tumor size (P = 0.04), recurrence (P <0.01), and eIF3f expression (P = 0.04) were all prognostic predictors of human GC after resection." (PMID 24678890, 2014). "Our findings established a new mechanism of rRNA decay regulation mediated by hnRNP K/eIF3f and suggest that the tumor suppressive function of eIF3f may link to impaired rRNA degradation and translation." (PMID 22457825, 2012). "Our findings establish the physiologic role of eIF3f in rRNA degradation and translation, and suggest that the tumor suppressive function of eIF3f may link to impaired rRNA degradation and translation." (PMID 22457825, 2012). "To validate the relevance of our findings to human CRC and to examine whether hindering eIF3f‐PHGDH signaling axis can restrain the CRC tumor formation, we performed cell growth studies and the results showed that both NCT‐503 and LGK‐974 (Wnt inhibitor) could suppress CRC foci formation." (PMID 37544925, 2023). "In the tumor cells, enhanced eIF3F expression inhibits translation, cell growth, and cell proliferation and induces apoptosis, whereas knockdown of eIF3f inhibits apoptosis, showing the role of eIF3f as an essential negative regulator of cell growth and proliferation." (PMID 35884586, 2022). "We next explored whether eIF3f inhibits tumor growth in vivo." (PMID 26988917, 2016). "This complex enhances the EIF3F-mediated deubiquitination of FASN, increasing FASN stability and lipid synthesis, and accelerating tumor progression." (PMID 42231807, 2026). "Our results suggest that MNAT1, EIF3F, and PSMD10 are all highly expressed in the low differentiation state, indicating these key genes are critical factors promoting tumor malignancy." (PMID 41235252, 2025). "Significantly, administration of the PHGDH inhibitor NCT‐503 in the established eIF3f high PDX tumors (CRC#116, 216) attenuated tumor growth; while NCT‐503 had little impact on the growth of eIF3f low PDX tumors (CRC#309, 490)." (PMID 37544925, 2023). "Difference is found in the expression of EIF3A, EIF3B, EIF3D, EIF3F, EIF3H, EIF3J, and EIF3M in different tumor stages." (PMID 36051357, 2022). "We next investigated the inhibitory effect of eIF3f on CLU expression and Akt and ERK signaling pathway in tumor tissues harvested from control and eIF3f treated mice." (PMID 26988917, 2016). "The EIF3F and EIF3E have characteristics similar to tumor inhibitory factors, which inhibit the cell proliferation and promote apoptosis." (PMID 22734884, 2012). "The combination of NCT‐503 and LGK‐974 was more efficient in suppressing tumor growth than NCT‐503 or LGK‐974 alone in the eIF3f high‐expressing PDX tumors, while the efficacy of these drugs on the eIF3f low‐expressing PDX tumors was compromised in terms of tumor volume and weights." (PMID 37544925, 2023). "This analysis revealed a subgroup of patients, 20% of the total population, with EIF3F expression level higher in the tumor as compared to the noncancer tissue (Z′ > 1.3-fold)." (PMID 31527668, 2020). "However, eIF3f expression was not significantly correlated with sex (P = 0.87), age (P = 0.17), tumor differentiation (P = 0.46), and tumor size (P = 0.16)." (PMID 24678890, 2014).
neurodevelopmental disorder (3 papers, 2021 to 2024). A behavioral and cognitive disorder with onset during the developmental period that involves impaired or aberrant development of intellectual, motor, or social functions. "Bi-allelic variants in the EIF3F gene have recently been published as the cause for a syndromic neurodevelopmental disorder (NDD) (OMIM #618,295: intellectual developmental disorder, autosomal recessive 67)." (PMID 33736665, 2021). "Instead, we identified several rare, likely pathogenic variants in seven genes implicated in neurodevelopmental disorders: KLHL17, TDO2, TRRAP, EIF3F, ATP10A, DICER1, and CDH15." (PMID 35743796, 2022). "To refine the phenotypic and molecular spectrum of EIF3F-related neurodevelopmental disorder, we examined independent patients." (PMID 33736665, 2021).
infection (2 papers, 2008 to 2018). The state of being infected such as from the introduction of a foreign agent such as serum, vaccine, antigenic substance or organism. "In fact, infection of cells stably expressing the Flag-tagged eIF3f with IBV showed reduced virus production, compared with cells without expression of the protein." (PMID 18231581, 2008). "Slightly more induction (1.02-fold) of IL-6 mRNA in cells without expressing the Flag-tagged eIF-3f was observed at 16 hour post-infection (lanes 3 and 7)." (PMID 18231581, 2008). "Quantitative analysis by densitometry showed that 6-, 2.58- and 0.82-fold more IL-8 was present in cells expressing the Flag-tagged eIF3f than that in cells without expressing the Flag-tagged eIF3f at 12, 16 and 24 hours post-infection, respectively (lanes 3–5 and 8–10)." (PMID 18231581, 2008).
EIF3F also shares sentences with these, for which no sentence is quoted: diabetes (2 papers); Intellectual disability (2); viral infection (2); ZIKV infection (2); Acute hepatitis (1); autism spectrum disorder (1); brain tumor (1); breast tumors (1); colon cancer (1); gastric tumor (1); hepatocellular carcinoma (1); liver diseases (1); melanocytic neoplasm (1); meningioma (1); microcephaly (1); mole (1); neurological disorders (1); Peri-Implantitis (1); Synthesis (1); type 2 diabetes mellitus (1); vulvar cancer (1).